POMC (proopiomelanocortin)
Diseases named in the same sentence as POMC in open-access papers (continued):
Sharing a sentence is not in itself a finding about the gene and the disease.
Insulin resistance (87 papers, 2009 to 2025). Increased resistance towards insulin, that is, diminished effectiveness of insulin in reducing blood glucose levels. "Previous studies have found that selective decrease in arcuate nucleus insulin receptor levels, and increase in POMC can cause weight gain, increased adiposity, and rapid onset of hepatic insulin resistance 70,71." (PMID 39005353, 2024). "Our observations that SK3 deficiency in POMC neurons causes glucose intolerance and insulin resistance in female mice are consistent with a possibility that enhanced POMC neuron activity leads to increased release of β-endorphin." (PMID 36210455, 2022). "The loss of IRE1α in POMC neurons accelerates ER stress and predisposes POMC neurons to insulin resistance." (PMID 33329397, 2020). "Deletion of leptin and insulin receptors in POMC neurons cause hyperinsulinemia and insulin resistance with higher LH and testosterone levels in intact female mice compared to control." (PMID 25780937, 2015). "Thus, Sel1L deficiency in POMC neurons leads to age-associated adiposity accompanied by hyperleptinemia, hyperinsulinemia, and insulin resistance." (PMID 29457782, 2018). "Specifically, we found that POMC neuronal activation is indispensable for energy homeostasis and insulin resistance triggered by MC4R knockdown-induced Kir2.1 activation in the state of HFD." (PMID 38448811, 2024). "In summary, this study demonstrates that MC4R selectively in the ARC contributes to energy balance and insulin resistance by reducing the activation of POMC neuron via hypothalamus Kir2.1." (PMID 38448811, 2024). "Two main populations of neurons, POMC and AgRP, express leptin receptor and insulin receptor, and insulin action in these neurons affected systematic insulin resistance." (PMID 36042571, 2023). "We showed that POMC-specific SK3 deficiency increased fasting glucose and caused glucose intolerance and insulin resistance in female mice." (PMID 36210455, 2022). "Surprisingly, POMC-specific insulin receptor knock-in mice show exacerbated insulin resistance and increase HGP36." (PMID 33293550, 2020). "Together, this suggests that altering leptin signaling in POMC neurons results in rapid-onset hepatic insulin resistance." (PMID 29528284, 2018). "Here, we found that POMC deletion in hypothalamic neurons leads to glucose intolerance and insulin resistance only in females." (PMID 30283405, 2018). "POMC-specific induction of XBP1s expression led to the decrease of leptin and insulin resistance, as well as diet-induced obesity even under treatment with strong activators of ER stress like tunicamycin and thapsigargin." (PMID 29921793, 2018). "In vivo POMC-specific Cacna1e knockdown increased hepatic glucose production and insulin resistance, while body weight, feeding, or leptin-induced suppression of food intake were not changed." (PMID 30304668, 2018). "Specifically, removing LEPRs from POMC neurons in adult mice resulted in insulin resistance and impaired hepatic glucose production within one week following deletion." (PMID 29528284, 2018). "Our studies indicate that the inhibition of POMC neurons promotes hepatic gluconeogenesis and whole-body insulin resistance, whereas the activation of POMC neurons represses HGP." (PMID 30230471, 2018). "Nonetheless, the combined deletion of the IR plus leptin receptor in POMC neurons profoundly affects glucose homeostasis and results in systemic insulin resistance and increased HGP." (PMID 30230471, 2018). "We show that deletion of Rps6kb1 in POMC neurons leads to defective regulation of HGP, while deletion in AgRP neurons causes skeletal muscle insulin resistance." (PMID 25865886, 2015). "The hepatic insulin resistance seen in leptin receptor null mice is normalized by genetic reactivation of leptin receptors specifically in POMC neurons in a weight-independent fashion." (PMID 23550218, 2013).
Insulin resistance (continued). "Notably, we observed an intermediate phenotype in male and female AgRP-Gq;POMC-Gi mice, where simultaneous inhibition of POMC neurons partially rescues the insulin resistance phenotype resulting from activated AgRP neurons." (PMID 38378998, 2024). "Notably, the concurrent inhibition of POMC neurons with AgRP neuronal activation partially rescued the insulin resistance induced by AgRP neuron activation." (PMID 38378998, 2024). "Taken together, we speculate that MC4R-specific knockout in the arcuate nucleus upregulates Kir2.1 expression and inhibit POMC neuron activity, thereby increasing intake and insulin resistance in mice." (PMID 38448811, 2024). "It was hypothesized that LE would suppress hypothalamic ERS and normalize POMC/AgRP neuronal activity, alleviate hyperphagia and consequently reduce fasting blood glucose and insulin resistance in diabetic mice." (PMID 37415911, 2023). "However, deletion of both insulin and leptin receptors from POMC neurons deteriorates glucose homeostasis and specifically leads to systemic insulin resistance and impaired fertility in mice." (PMID 28592656, 2017). "Interestingly, when both leptin and IR were ablated in POMC neurons, systemic insulin resistance despite increased pancreatic insulin secretion was observed in these mice." (PMID 25538630, 2014). "5HT2C null mice have increased body weight and hepatic insulin resistance and reactivation of 5HT2C receptors specifically in POMC neurons normalizes hepatic insulin sensitivity suggesting that these specific receptors are sufficient to regulate energy and glucose homeostasis." (PMID 23550218, 2013). "Therefore, modulation of insulin sensitivity through the opposing actions of AgRP activation and POMC inhibition may converge in the liver to counteract the development of systemic insulin resistance." (PMID 38378998, 2024). "Whether Adipo signal impacts the activity of peripheral skeletal muscle protein kinase and glucose absorption through the regulation of POMC neurons, and whether the regulation of Adipo signal by POMC neurons plays a key role in improving insulin resistance remain unclear." (PMID 37034166, 2023). "MC4R-deficient mice develop insulin resistance without enhancement in beta cell function, and the improved glucose tolerance is attributed to glycosuria caused by reduced renal sympathetic nerve activity, similar to the mechanisms in POMC-deficient mice." (PMID 36210455, 2022). "Inhibition of AKT phospholation in POMC neurons induced age‐ and diet‐related insulin resistance, while, increasing PI3K activity, the upstream of AKT, in POMC neurons improved insulin and glycemic responses." (PMID 36042571, 2023). "In the hypothalamus, metabolism enhancing TTR expression was upregulated, and the PTPN1 level denoting insulin resistance was downregulated, while NPY, AGRP, POMC, CART levels denoting leptin resistance showed a normalizing trend." (PMID 32943760, 2021). "On the other hand, POMC-specific deletion of PTP-1B and PTP-1B knockdown in the hypothalamus by antisense oligonucleotide protects animals from HFD-induced obesity and insulin resistance." (PMID 30875909, 2019). "Genetic deletion of Ire1α in pro-opiomelanocortin (POMC) neurons induced ER stress, as well as leptin and insulin resistance in these cells." (PMID 29921793, 2018). "Knockdown of Kir2.1 in POMC neuron-specific ablation of MC4R restored the effect of MC4R ablation on energy expenditure and systemic glucose homeostasis, indicating by reduced body weight and ameliorated insulin resistance." (PMID 38448811, 2024). "In both insulin resistance (IR) and non-IR states, Stattic significantly inhibited p62-mediated POMC expression in N2a cells." (PMID 39479445, 2024). "Moreover, the hyperactivated STAT3 induces the suppression of the 3-phosphoinositide pathway and, as a result, provokes the leptin and insulin resistance in the hypothalamus, as was shown in mice expressing a constitutively active STAT3 in the POMC-neurons." (PMID 30870482, 2019).
Insulin resistance (continued). "Genetic deletion of S6K in POMC neurons does not affect food intake or weight, and surprisingly induces insulin resistance, which contradicts the results obtained in postnatal overexpression models using viral vectors." (PMID 30875909, 2019). "Long-term exposure to a “Westernized” HFD causes sexually differentiated insulin resistance that, among other things, is associated with a reduced insulin receptor-mediated activation of TRPC5 channels in POMC neurons from male but not female guinea pigs." (PMID 29973869, 2018). "Interestingly, this attenuation of AgRP neuron-induced insulin resistance following concomitant POMC neuron inhibition occurred independent of a rescue in BAT glucose uptake, arguing that this partial restoration occurs via alternative mechanisms." (PMID 38378998, 2024). "Thus, the reduction in ARC PI3K/Akt signaling seen with obese/insulin resistance could pave the way for testosterone-induced AMPK activation in males that increases EC and N/OFQ tone at SF-1/POMC synapses." (PMID 30755252, 2019). "As shown presently and reported recently, insulin purified from guinea pig and other animal sources also depolarizes POMC neurons via a PI3K-induced activation of TRPC5 channels, and these neurons are a critical substrate in the development of sexually differentiated diet-induced insulin resistance." (PMID 29973869, 2018). "Interestingly, female mice lacking estrogen receptor alpha only in POMC neurons develop insulin resistance and glucose intolerance." (PMID 30283405, 2018). "In either case, we speculate that sexual dimorphism found in our study is a consequence of estradiol (E2) facilitation of POMC activity since it was previously shown that estradiol prevents insulin resistance in POMC neurons of diet induced obese female but not male mice." (PMID 30283405, 2018). "The absence of POMC signaling in PomcNULL mice leads to reduced sympathetic nerve activity to the kidney and as a result, a downregulation of GLUT2, and extreme insulin resistance without elevated glucose." (PMID 29031711, 2017).
neuroendocrine tumors (87 papers, 2005 to 2026). "Some POMC‐derived peptides have been reported to have vital roles in neuroendocrine tumors such as guiding optimal choice of chemotherapy." (PMID 37830163, 2024).
Hyperglycemia (77 papers, 2009 to 2026). An increased concentration of glucose in the blood. "On the other hand, reactivation of central POMC at different stages of development in neural-specific POMC deficient mice reduces food intake and weight gain and attenuates comorbidities such as hyperglycemia and hyperinsulinemia." (PMID 25538630, 2014). "In line with this study, Berglund and colleagues confirmed that physiological re-expression of LEPRs only in POMC neurons in the ARC brings about normalization of the hyperglycemia caused by an otherwise complete LEPRs deficiency." (PMID 24589844, 2014). "Overall, maternal hyperglycemia increased the vulnerability of females developing metabolic impairments, since they showed increased body weight gain, and this was associated with changes in gestational and adult POMC protein immunocytochemical expression in ARC." (PMID 37396180, 2023). "It is noteworthy that the POMC-Cre ERt2:: FASNflox/flox mice also secreted significantly less insulin in response to hyperglycemia as early as 15 min after infusion started." (PMID 40541585, 2025). "A recent study from our group showed that maternal hyperglycemia during pregnancy affects offspring POMC expression in a sex‐dependent manner." (PMID 40474775, 2025). "Conversely, re-expression of Lepr selectively in POMC neurons completely normalizes hyperglycemia and improves insulin sensitivity." (PMID 38027481, 2023). "Hypothalamic POMC rescue in obese mice also attenuates hyperglycemia, hyperinsulinemia, and hepatic steatosis." (PMID 33293550, 2020). "Positive energy balance, which is characterized by hyperglycemia and glycolytic metabolism, activates POMC neurons and generates significant ROS that acts as an endogenous intracellular feedback signal in POMC neurons to control activity." (PMID 23730258, 2012). "The absence of a maternal hyperglycemia effect may be due, in part, to increases in POMC expression in the ARC that were observed following maternal hyperglycemia and HFD exposure, which might increase insulin sensitivity and, thus, glucose tolerance." (PMID 37396180, 2023). "In this sense, our data confirm previous data using a similar STZ model on mice and shows that POMC neurons in the ARC of female offspring may be particularly vulnerable to maternal hyperglycemia." (PMID 37396180, 2023). "In contrast to POMC neurons, deleting of Lepr in AgRP neurons produces hyperphagia and hyperglycemia, resulting in massive weight gain that reaches about 80% of the weight observed in db/db mice, suggesting AgRP neurons play important roles in mediating leptin’s effects on energy balance." (PMID 38027481, 2023). "However, as Arc GABAergic LepRArc neurons are the primary mediator of the leptin action in T1D, POMC neurons, which are non-GABAergic21, may contribute little to T1D hyperglycemia and leptin action in reducing T1D glucose." (PMID 33976218, 2021). "In vivo studies showed that lateral intracerebroventricular (i.c.v.)injection of glucose in mice mimics hyperglycaemia at 2 hrs after the injection, as detected by reduced NPY and increased POMC mRNA levels, which was correlated with the cessation of FI 63,64." (PMID 26081217, 2015). "Interestingly, in adulthood, there was an increase in POMC neurons in the offspring of STZ-treated dams, showing that postnatal development of the melanocortin system was also affected by maternal hyperglycemia." (PMID 37396180, 2023). "However, unlike WT mice, CRF-OE mice display sex differences in the fasting hyperglycemia and hypothalamic NPY and POMC mRNA levels with females > males." (PMID 28101317, 2017). "Interestingly, exposure to maternal hyperglycemia only during lactation (i.e., through maternal milk) was sufficient to decrease both POMC and α‐MSH neurons in the ARC, with no changes in NPY neuronal number." (PMID 40474775, 2025). "Interestingly, feeding-induced hyperglycemia was higher in mice lacking LEPRs in adult POMC neurons." (PMID 29528284, 2018).
Hyperglycemia (continued). "It is to be determined whether or not POMC is involved in improvement on hyperglycemia in our model since POMC regulates glucose homeostasis and insulin sensitivity through distinct CNS populations from those regulating food intake and body weight." (PMID 23326534, 2013). "Despite the increased number of POMC neurons following maternal hyperglycemia and HFD intake in adulthood, there were no changes in POMC projections to the PVN, which might also explain why a higher number of POMC neurons was not sufficient to decrease food intake in those offspring." (PMID 37396180, 2023).
melanoma (73 papers, 1990 to 2026). A malignant, usually aggressive tumor composed of atypical, neoplastic melanocytes. "POMC is mainly secreted in the hypothalamus and acts as a precursor polypeptide hormone and is associated with the morphological differentiation and the production of melanin in B16-F10 melanoma cells." (PMID 41394903, 2025). "Systemically, POMC derivatives influence skin pigmentation, immune function, endocrine responses, and nervous system activity, with significant implications for melanoma development, metastasis, and systemic responses." (PMID 40331942, 2025). "POMC and its derivatives exert multifaceted effects on melanoma progression and systemic physiology." (PMID 40331942, 2025). "In fact, increased expression of POMC, its peptides, and its regulators were noted during melanoma progression." (PMID 38927967, 2024). "POMC peptides, including melanocyte-stimulating hormone (MSH), are immunosuppressive, and an increased expression of POMC peptides was noted during the progression of melanomas to advanced stages." (PMID 38474231, 2024). "Supplementary, desmoglein 1 is involved in the signalling between melanocytes and keratinocytes, with cytokines and POMC production, leading to a high level of melanin and pagetoid melanoma cells spread." (PMID 35334544, 2022). "POMC also acts on the melanoma tumor microenvironment by reducing the neo-vascular network, thus demonstrating its potential role as a future treatment avenue." (PMID 34068618, 2021). "Systemic administration of POMC was evaluated as melanoma therapy in mice, where it was evidenced that POMC overexpression prolonged survival." (PMID 34068618, 2021). "Our previous study showed that the inhibition of inflammatory COX-2/PGE2 signaling contributed to the POMC-mediated melanoma suppression in vitro and in vivo." (PMID 31968661, 2020). "Quantification analysis further indicated that the Bax/Bcl-2 ratio and LC3-ΙΙ/LC3-Ι conversion were significantly increased in Ad-POMC-infected melanoma tissues." (PMID 30062060, 2018). "By GFP-LC3 puncta formation assay, it was found that POMC gene delivery marginally promoted the GFP-LC3 puncta spots in melanoma cells under normoxic condition." (PMID 30062060, 2018). "Similar to this notion, the present study has shown that POMC-induced autophagy contributed to cell apoptosis in melanoma cells during hypoxia." (PMID 30062060, 2018). "By histological and immunoblot analysis, it was shown that POMC-treated melanoma tissues exhibited the prominent LC3 immunostaining, which was correlated with reduced CD31-positive tumor vascularization." (PMID 30062060, 2018). "In this study, we investigated the crosstalk between autophagic and apoptotic signaling in POMC-mediated melanoma suppression." (PMID 30062060, 2018). "We then utilized the POMC-derived peptide α-MSH with CoCl2 to elicit the autophagy as well as apoptosis in cultured melanoma cells." (PMID 30062060, 2018). "In summary, the present study unveils that POMC gene therapy suppresses melanoma through activation of both autophagic and apoptotic signaling pathways in melanoma cells." (PMID 30062060, 2018). "This was further validated by cell culture studies, in which POMC gene delivery elevated LC3-positive autophagosome formation in melanoma cells under hypoxia." (PMID 30062060, 2018). "We subsequently delineated that the POMC-derived α-MSH was sufficient to evoke the autophagy as well as apoptosis in melanoma cells in the presence of CoCl2." (PMID 30062060, 2018). "Strikingly, POMC gene delivery significantly stimulated the GFP-LC3 puncta formation in melanoma cells during hypoxia by cobalt chloride (CoCl2)." (PMID 30062060, 2018).